VHL (von Hippel-Lindau tumor suppressor)
Diseases named in the same sentence as VHL in open-access papers (continued):
Sharing a sentence is not in itself a finding about the gene and the disease.
tumor (continued). "As the key protein of VHL syndrome, pVHL regulated the expression of different tumor genes." (PMID 33828526, 2021). "Consequently, these alterations play a crucial role in the modification of signaling networks and tumor pathogenesis, and RCC patients with the VHL mutation are characterized by having a poor prognosis." (PMID 34359798, 2021). "Both tumor subtypes lack VHL or chromosome 3p abnormalities." (PMID 34885018, 2021). "This work shows a novel mechanism for VHL tumor progression." (PMID 34563045, 2021). "This can be achieved pharmacologically by applying PROTACs that target BCL-XL for ubiquitination (and thereby for proteasome-mediated degradation) within the tumor microenvironment, but these PROTACs cannot eliminate platelets because the expression of VHL or CRBN in platelets is minimal." (PMID 33627663, 2021). "A previous study has reported that the von Hippel-Lindau (VHL) tumor suppressor could change the expression of miRNA." (PMID 34307682, 2021). "It would be intriguing to explore whether Smurf2 plays a tumor suppressive role alternatively to VHL in this context through targeting HIF-α." (PMID 34611473, 2021). "Disrupting the VHL/HIF-α interaction may affect the HIF-independent tumor suppressor function of pVHL." (PMID 34943817, 2021). "However, it was demonstrated that Src attenuation by CBD caused the stabilization of VHL as well as the downregulation of HIF-1α and VEGF, followed by the inhibition of tumor angiogenesis under hypoxic conditions." (PMID 34830821, 2021). "In addition, the VHL–HIF pathway is further enhanced due to the effect of the hypoxic TME that occurs with tumor progression." (PMID 34575959, 2021). "Consequently, although VHL is the main player in the pathobiology of ccRCC, these other tumor suppressor clusters are also likely to be involved; in fact, recent studies have shown that VHL inactivation alone is not sufficient for the development of ccRCC." (PMID 34575959, 2021). "VHL was demonstrated to contribute to the function of CPSF6-mediated tumor growth in GC cells." (PMID 34594359, 2021). "miR-155 stimulates tumor angiogenesis and proliferation by targeting VHL." (PMID 34778378, 2021). "Mechanistically, a large number of biomolecules and tumor-associated signaling pathways, including DECR1, PANX2, HSPB1, ACOT8, SUV39H1, NCOA4, PI3K-AKT-mTOR signaling, VHL/HIF-2α pathway, and Hippo/TAZ signaling pathway, have been reported to regulate ferroptosis in urologic cancers." (PMID 34922551, 2021). "Therefore, identification of VHL-related lncRNAs and further exploration of their regulatory mechanisms can provide new theoretical basis for tumor therapy." (PMID 33854630, 2021). "Similar to VHL, PBRM1 is often mutated early during tumor development." (PMID 34885018, 2021). "VHL mRNA was found to be generally overexpressed in the ccpRCC tumour compared with non-neoplastic renal parenchyma and ccRCC cases carrying 3p losses and/or VHL mutations, despite the absence of VHL inactivating mutations or chromosome 3p losses." (PMID 35008576, 2021). "VHL mediates tumor invasion and metastasis by regulating HIFs protein expression." (PMID 34923986, 2021). "Therefore, we used generated multiple sunitinib-resistant clones in primary tumour ccRCC cell lines that are VHL-defective (786-O and A498) and the metastatic, VHL-functional, Caki-1 cell line." (PMID 34503211, 2021).
tumor (continued). "When concerning the correlation between these VHL-related lncRNAs and the progression of ccRCC, most of them were closely related to some clinical parameters of ccRCC, including tumor stage, lymphatic invasion, metastasis, pathological stage and histological grade." (PMID 33854630, 2021). "Furthermore, this study displays RFA ́s ability to achieve tumor control in larger tumors than reported previously in VHL patients, where lesion size ranged from 1.9 to 2.6 cm." (PMID 34414496, 2021). "The variant allele of rs1642742 may affect the ability of miRNA to bind to its sequence, which in turn affects the VHL gene expression and may lead to tumor metastasis." (PMID 34477178, 2021). "Even though the most common and well-known mutation identified in clear cell RCCs is the VHL tumor suppressor gene, it has no prognostic or predictive value in patients with clear cell RCC." (PMID 31901171, 2020). "Next, we look at VHL expression, an important tumor suppressor gene." (PMID 32211322, 2020). "This indicates that FLCN contributes to the tumor-suppressing effect of VHL." (PMID 33643028, 2020). "However, experimental findings suggest that both HIF-dependent and HIF-independent mechanisms are essential for VHL-mediated tumor suppressor effects." (PMID 32788634, 2020). "DT2216, a representative PROTAC that hijacks the VHL E3 ligase to achieve tissue/cell-selective degradation of Bcl-xL, was found to be more potent against Bcl-xL-dependent tumor cells and less toxic against platelets in comparison to conventional Bcl-xL inhibitors." (PMID 32718354, 2020). "In such a scenario, our data suggest that there is no specific advantage for tumor cells to use the specific combination of deletion and mutation for knocking out the VHL gene." (PMID 32076485, 2020). "The VHL gene mutation status was analyzed in 9 samples, and in cases 22, 23 and 31 a pathogenic mutation was identified that was not present in the tumor-free renal parenchyma." (PMID 31656019, 2020). "VHL, the Von Hippel-Lindau disease tumor suppressor protein possesses an E3 ligase activity." (PMID 32731489, 2020). "Thereafter, the von Hippel Lindau (VHL) tumor suppressor functions as an E3 ubiquitin ligase to mediate the ubiquitination of HIF-1α by specifically binding to these two prolyl-hydroxylated residues, eventually leading to rapid proteasomal degradation of HIF-1α protein." (PMID 32014012, 2020). "Therefore, the in vitro and in vivo antitumor benefits of propranolol (ADRB-1,2 antagonist) and ICI-118,551 (ADRB-2 antagonist) on VHL−/− ccRCC primary cultures and 786-O tumor cell lines have been addressed." (PMID 32854260, 2020). "Age-related risks of overall VHL-associated tumors or each VHL tumor were similar between NoF2 subgroup and oTR group." (PMID 33362845, 2020). "HIF-1α protein stability is dependent on VHL, a tumor suppressor gene that downregulates HIF-1α." (PMID 32707933, 2020). "In addition, VHL tumor suppressor gene inactivation has also several HIF-independent effects including cell cycle regulation and apoptosis." (PMID 32507909, 2020). "Because the activation of EGFR and TGFα autocrine loop occurs in changing cysts of multiple target organs, this pathway might be exploited as a potential target for anti-tumor therapy for VHL patients." (PMID 32432044, 2020). "In the kidney, VHL is presumed as an early tumor suppressor gene where genetic and epigenetic events (either by mutation, loss of heterozygosity or hypermethylation of the promoter) are required for tumorigenesis and it has been documented in up to 80% of the sporadic ccRCC." (PMID 32854260, 2020). "For instance, Von Hippel-Lindau (VHL) modification by NEDD8 is significant for tumor suppression." (PMID 33097763, 2020).
tumor (continued). "Besides VHL, frequent genetic mutations have been detected in BAP1, PBRM1, and SETD2, all of which are related to chromatin and histone regulation and serve as tumor suppressor genes in kidney cancer." (PMID 31739630, 2019). "To date, early inactivation of the VHL gene, encoding a ubiquitin ligase, which marks hypoxia-induced factor α (HIF-1α) for proteasomal degradation, thus responsible for cellular oxygen sensing, is pointed out as a key tumor suppressor gene impaired in ccRCC." (PMID 31921677, 2019). "Variant calling of the t/RNA-NGS datasets revealed mutations in the VHL gene in tumor samples of four of the patients, which were not present in matched healthy kidney tissue, identifying these as somatic mutations." (PMID 30881919, 2019). "Furthermore, we prove that targeting RSUME in RCC cell line clones carrying missense VHL mutants results in decreased early tumor angiogenesis." (PMID 30890701, 2019). "Likewise, HIF-1α subunit, is negatively regulated by the VHL tumor suppressor and miR-155 has been shown to downregulate the expression of VHL tumor suppressor, a protein involved in the cellular response to hypoxia." (PMID 30842790, 2019). "In the present study, we used targeted next-generation sequencing for mutation analysis of primary tumor tissues from 50 patients metastatic RCC, and we detected Nrf2 gene mutation in 5 patients, Keap1 gene mutation in 11 patients, and VHL gene mutation in 35 patients." (PMID 31752777, 2019). "Studies on the average onset ages of VHL-related tumors have helped the VHL Alliance to propose the VHL tumor surveillance regimen for the last decades, according to which routine imaging screening should start at 1 year old for RA, 8 for PHEO, 16 for CHB, and 8 for RCC and PCT." (PMID 31068970, 2019). "Generally, ccRCC is a highly vascularized tumor, in which the von Hippel Lindau (VHL) tumor suppressor gene is frequently inactivated, leading to the overexpression of the hypoxia-inducible factor (HIF)-2α oncoprotein and its downstream targets like the vascular endothelial growth factor (VEGF)." (PMID 31259150, 2019). "The median VHL mRNA expression level in the 64 tumours was 7.82 (range: 6.96–8.60)." (PMID 31323773, 2019). "Conversely, abnormal DNA methylation is related to the occurrence of several human diseases, with many studies showing the role of aberrant DNA methylation in the activation of tumor promoter genes (e.g., MAGE, S100P) and silencing of tumor suppressor genes (e.g., VHL, MLH1) in various cancers." (PMID 30833961, 2019). "Regardless of whether the patient has co-occurring VHL and BAP1 mutations or co-occurring VHL and PBRM1 mutations, T cell activation genes form coordinated co-expression in the tumor." (PMID 30814637, 2019). "Considered that several phosphorylation sites appeared to be mutated in tumor samples from patients, we wondered whether alteration of other post translational modification (PTM) sites may play a role in VHL progression." (PMID 30943211, 2019). "VHL is a tumor-suppressor gene that is located on chromosome 3p25.3 and encodes the pVHL protein." (PMID 30925729, 2019). "In addition to this, sumoylation of other components of the HIF system such as hypoxia associated factor (HAF) has been connected with the reprograming of HIF-2 response during VHL loss, needed for RCC tumor progression." (PMID 30890701, 2019). "Tumour size only had a role in VHL expression in D3 lesions." (PMID 31323773, 2019).
tumor (continued). "Four of these cases (ID69, ID66, ID67 and ID24) had a somatic variant in a known PPGL susceptibility gene (SDHB, SDHD, and 2x VHL) that was not present in the matched blood sample, indicating a sporadic tumor development in these cases." (PMID 31212687, 2019). "Similarly, BAP1-negative tumours (n = 30) had a higher expression of HIF1a (p < 0.001) and a lower expression of VHL (p = 0.003) compared to BAP1-positive tumours (n = 24)." (PMID 31323773, 2019). "For example, solid tumors without VHL mutation contain 0–60% hypoxic tumor areas with CAIX expression -as assessed immunohistochemically- whereas tumors with the VHL-mutation show CAIX expression above 85% on average." (PMID 31827111, 2019). "We evaluated how the expression of HIF1a and VHL relates to clinical and genetic factors in UM and established that genetics, but not tumour size, are strongly associated with the level of these markers." (PMID 31323773, 2019). "In ccRCC, von Hippel Lindau (VHL), a tumor suppressor, is dominantly inactivated." (PMID 31221981, 2019). "Hence, cells from VHL tumours have a constitutively active HIF program (a pseudo-hypoxic state) due to the absence of functional pVHL6,7." (PMID 31296894, 2019). "Remarkably, the type of VHL mutation detected in the 57 validated CCC, as well as in 104 CRC-UMF, correlated exactly with that detected in the corresponding tumor samples, strongly suggesting the neoplastic nature of at least some cells classified as CRC-UMF by the cytopathologists." (PMID 29732003, 2018). "This suggests that in the majority of the pNETs analyzed, tumor hypoxia gene expression profiles are due to pseudohypoxia caused by disrupted VHL function rather than true hypoxia." (PMID 30062048, 2018). "However, patients with LOF mutations obtained a significantly higher response rate than those with VHL-wild-type tumor (52% vs. 31%, p = 0.04)." (PMID 30149673, 2018). "Our molecular results thereby showed a complete correlation of absence of VHL mutation in the tumor and in the corresponding CCC and CRC-UMF derived from the same 4 patients." (PMID 30177639, 2018). "Subsequently, two independent sets (n = 532 and 105) verified the high level of SERPINH1 in ccRCC tissues and its association with reduced overall survival and disease‐free survival in all tumour‐node‐metastasis stages and patients with von Hippel–Lindau wild‐type (VHL‐WT)." (PMID 29239102, 2018). "In the absence of VHL mutation in the RCC the matrix FN is strong with absence of FN in the tumour cell cytoplasm." (PMID 30009029, 2018). "We therefore sorted the tumor samples into groups with and without VHL point mutations and groups with copy number alterations of 0/1, -1, or -2." (PMID 29435132, 2018). "Tumor tissue DNA analyses from the 30 patients included in this study revealed that four patients (13.3%) had no detectable VHL mutations in their tumor samples." (PMID 29732003, 2018). "EMT can be regulated by von Hippel–Lindau (VHL), a notable tumour suppressor in ccRCC." (PMID 29239102, 2018). "Interestingly, though strong HIF2α staining has been shown in both VHL-mutated and SDH-mutated tumours, PPGL with HIFα mutations demonstrate a different pseudohypoxic transcriptome, suggesting that a further transcriptional driver is involved." (PMID 29450727, 2018). "One tumor harbored a clonal mutation in the TCEB1 gene, a part of the VHL complex, thus 90% (95/106) of the tumors harbored clonal disruption of the VHL pathway." (PMID 29656894, 2018). "The remaining 7 CCC and 16 CRC-UMF without VHL mutation were all found to derive from the 4 patients harboring a wild type VHL sequence in their tumor tissues." (PMID 30177639, 2018). "Independent of VHL deficiency, hypoxia is an important physiological component of solid tumors and contributes to tumor progression and metastasis." (PMID 29435132, 2018).
tumor (continued). "In addition to the upregulation of hypoxia inducible factors due to enhanced VHL-HIF signaling pathway RCC also exhibit tumor hypoxia due to low oxygen pressure within the tumor." (PMID 30123419, 2018). "Our molecular results showed a complete correlation of absence of VHL mutation in the tumor and in the corresponding CCC and CRC-UMF." (PMID 29732003, 2018). "VHL is a tumor suppressor with known roles in tumorigenesis." (PMID 30340515, 2018). "Moreover, in an autologous setting, IL-2 activated NKs isolated from RCC-VHL-MUT patients more efficiently degranulated toward RCC autologous tumor cells or A498 VHL-MUT cells as compared to SN12C (RCC-VHL-WT) cell line." (PMID 30514329, 2018). "Accordingly, VHL downstream hypoxia signaling and tumor hypoxia might both trigger increased HMGB1 secretion, and result in increased VEGF signaling as well as total VEGF levels that bevacizumab can target." (PMID 30123419, 2018). "All five tumor pairs evolved independently, but converged on the VHL pathway." (PMID 29656894, 2018). "He found in a RCC patient there was HIF-1α diffuse granular staining in cytoplasm of tumour cells if there is presence of von Hippel-Lindau (VHL) gene mutation and no staining in the absence of VHL mutation." (PMID 30009029, 2018). "Furthermore, in patients diagnosed with ccRCC, several reports have shown that genetic alterations of the VHL locus are the only ubiquitous drivers found in the tumor, including when comparing multiple metastatic sites to the primary tumor." (PMID 29732003, 2018). "Although the mutation or deletion of VHL, is a promoting factor in the ccRCC type, VHL alone is not sufficient for tumor progression in RCCs." (PMID 29662646, 2018). "In addition, somatic mutations in the previously known genes VHL, RET, MAX, and HRAS were found in one tumor each, in agreement with frequencies in previous reports." (PMID 29159601, 2018). "The VHL gene is a tumor-suppressor gene located on the short arm of chromosome 3 (3p25.3)." (PMID 29789510, 2018). "The results support the notion that VHL influences DNA methylation early in disease and likely accounts for a significant proportion of the perturbations that are evident in the DNA methylome of tumours." (PMID 29463811, 2018). "The opposite TfR1 alterations in benign kidney and primary tumors during tumor progression might reflect contrasting tissue responses to iron accumulation due to VHL/PHD status." (PMID 29291011, 2017). "Given the relevance of telomeres and their function in tumor, we hypothesized that shorter blood telomere length is a new biomarker for age‐related tumor risks in VHL patients." (PMID 28776935, 2017). "Similarly, we observed six homozygous deletions over VHL, five of which take out the nearby tumour suppressor FANCD2 as well." (PMID 29089486, 2017). "However, no study has been carried out on the relationship between blood telomere length and age‐related tumor risks in VHL patients." (PMID 28776935, 2017). "In summary, we identified the reason why VHL behaves as both an oncogene and a tumor suppressor." (PMID 28580172, 2017). "Mean onset age of VHL‐related tumors was calculated from tumor‐affected patients." (PMID 28776935, 2017). "VHL mutations are associated with a strong HIF-1α-dependent miR-210 over-expression and accumulation of HIF-1α in most tumor cells whereas SDHx mutations are associated with mild increase of miR-210 and the presence of a heterogeneous, HIF-1α-positive and HIF-1α-negative, tumor cell population." (PMID 28036268, 2017). "Current data, however, suggest that VHL loss alone, though necessary, is not sufficient for tumour initiation in the kidney." (PMID 29229903, 2017). "VHL is a tumor suppressor gene located on chromosome 3p25.3." (PMID 28187001, 2017). "Importantly, the data obtained in the murine/cellular models were corroborated by the use of human tumor materials containing known alterations of the VHL and SDHx genes." (PMID 28036268, 2017).